CD4 (CD4 molecule)
Diseases named in the same sentence as CD4 in open-access papers (continued):
Sharing a sentence is not in itself a finding about the gene and the disease.
tumor (continued). "Our integration analysis results revealed a negative correlation between DEirlncRNA pairs and tumor‐infiltrating immune cells, such as B cells, CD4+ T cells, and CD8+ T cells." (PMID 34378851, 2021). "Moreover, CD40LG has a strong anti-tumor effect on HCC and other malignant tumors, while the CD40LG-CD40L interaction has been shown to overcome tumor-specific CD4+ and CD8+ tolerance and thus induce anti-tumor immunity." (PMID 35127491, 2021). "Tumor cells that are known to produce a variety of immunosuppressive factors such as PGE2, ADO, IL-10, and TGF-β, appear to play a major role in the conversion of CD4+CD25neg precursors to CD4+CD25+CD39+FOXP3+ Treg." (PMID 34442398, 2021). "Moreover, a significant (p < 0.05) increase in the CD4+ and CD8+ T cells of tumor-infiltrated and lymph node lymphocytes in the TEXomiR group compared with the PBS-treated group was demonstrated." (PMID 33987190, 2021). "CD4 lineage cells were associated with tumor development at 24 weeks of age when ERK-1/2 were conditionally deleted in CD4 lineage cells, with tumor development being accelerated in the absence of T cells." (PMID 34625577, 2021). "Besides, the expression patterns of CD4 and CD8 in tumor tissues can be a potential option for further investigation." (PMID 34380434, 2021). "In addition, by analyzing immune cell infiltration in tumor microenvironment, we found that immune-activated cells (CD8 T cells and memory activated CD4+ T cells) were significantly insufficient in the higher HIST3H2A expression." (PMID 34797282, 2021). "In the absence of CD4+ T cells, the 67NR cells formed primary tumours similar to wild-type mice also, it did not metastasise." (PMID 33795809, 2021). "Various immune cell types infiltrate the tumor microenvironment including T lymphocytes (CD3+ T cells, CD4+ Th cells, and CD8+ cytotoxic T cells), NK cells, MDSCs, macrophages, and dendritic cells that are involved in tumor progression and related to cancer prognosis." (PMID 34539666, 2021). "The majority of CD4+ T-cells are suppressive CD25+ forkhead box P3 (FOXP3)+ regulatory T-cells (Tregs), which are themselves recruited by tumor B-cells; it has been suggested that higher numbers of tumor-infiltrating FOXP3+ cells are associated with better response to H. pylori eradiation therapy." (PMID 34298992, 2021). "Interestingly, we found exhausted CD4+ T cells expressed not only high levels of CD47 but also the ligand Galectin-9 in the TME of both plaque and tumor MF." (PMID 34885092, 2021). "Conventional CD4+ T cells (Tconv) from vaccinated mice defined as non-Treg cells demonstrated a significantly greater proliferation capacity in tumor and dLNs." (PMID 34885215, 2021). "In one study, the depletion of CD4 using anti‐CD4 antibodies did not significantly affect the tumor‐growth inhibitory effects of E. coli, while the blockage of CD8 completely abolished antitumor efficacy." (PMID 34633664, 2021). "Interestingly, although increased anti-tumor immunity in transgenic mice required the presence of both CD8 and CD4 T cells, it required attenuation of TGF-β1 signals in CD8 T cells, but not in CD4 T cells." (PMID 34302795, 2021). "No increase was observed in the number of CD4+ or CD8+ Tconv cells within tumours of Ccr8−/− animals." (PMID 33838058, 2021). "Importantly, the number of CD4+ and CD8+ T cells and NK cells per one unit of tumor cell-emitting bioluminescence was also statistically significantly higher in WT1 peptide vaccine-treated mice than anti-PD-1 antibody-treated and control mice." (PMID 34355173, 2021). "In the present study, we analyzed the gene transcripts of presorted macrophages, CD4+ and CD8+ T cells from tumor and from adjacent normal lung with RNA-sequencing, which is followed by GO term enrichment and WGCNA, to identify mediators of immunosuppression in the TME in NSCLC." (PMID 33918618, 2021).
tumor (continued). "Spatial analysis revealed a differential distribution according to immune cells proximity to the tumour, with a decreasing proportion of proliferating CD3+ (P < 0.001), CD8+ (P < 0.001), CD4+ (P < 0.001) and Foxp3+ (P < 0.001) T cells from the intratumoural region (A) to the distal location (C)." (PMID 33742063, 2021). "Moreover, CD38 expression was positive correlated with infiltrating levels of B cells, CD8+ T cells, CD4+ T cells, macrophages, neutrophils and dendritic cells in LUAD and LUSC, but negatively related to tumor purity." (PMID 33934206, 2021). "In this report, RFA initially enhanced a strong T-cell-mediated immune response in the tumor, and the tumor quickly overcame the immune responses by inhibiting the function of CD8+ and CD4+ T cells, driving a shift to higher regulatory T-cells and upregulating PD-L1/PD-1 expression." (PMID 34032770, 2021). "Although these data strongly suggest that Tregs recognize specific tumor antigens, albeit lower diversity compared to activated intratumoral conventional CD4+ cells, not all Tregs in the TME have tumor antigen-specific TCRs." (PMID 34177968, 2021). "The quantity of CD3+, CD4+, CD8+, Granzyme B+ and F4/80+ cells were dramatically increased at day seven after carbon ion radiation compared to the X-ray irradiated and untreated B16 tumours." (PMID 34732697, 2021). "Nonetheless, it is not clear how CD4 CTLs can directly engage target cells at the molecular levels when MHC Class II restriction is not applied or the tumor lacks HLA Class II expression." (PMID 33968044, 2021). "MiR-138 acts as a tumor suppressor in many types of cancer and, through its binding at the 3′UTR of CTLA-4 and PD-1, reduces glioma cell growth in vivo by suppressing immune checkpoint expression in human CD4+ T lymphocytes." (PMID 33808190, 2021). "Furthermore, it enhances the in vivo function of CD4+ and CD8+ T cells in the tumor-draining LN, an important location for T cell priming." (PMID 33408092, 2021). "Although the ways are not the same in different tumor cell lines, an increase of CD4+ effector memory T cell (TEM) population in the PB and spleen was common in huNOG-FcγR−/− mice." (PMID 34702924, 2021). "In a subsequent trial, DCs were engineered with three tumor antigens (tyrosinase, MART-1 and MAGE-A6) to activate multiple CD8 + and CD4+ T cell clones and patients were randomized to receive a one-month course of high-dose systemic IFN-α2b following vaccination or vaccination alone." (PMID 33407605, 2021). "Treatment results showed that Rag2−/− tumors were markedly reduced by infusing Ogr1−/−-CD8+ T cells, whereas the difference in tumor weight between the treatments of infused Ogr1−/−-CD4+ T cells and infused WT-CD8+ T cells did not significantly change." (PMID 34158625, 2021). "CD4+CD8+ T cells are increased in urologic cancers patients and found to be high type-2 cytokine producers favoring a Th2 response in vitro while inhibiting Th1 cells known to play a crucial role in anti-tumor immunity." (PMID 34677693, 2021). "Moreover, clinical trials showed the efficacy of chemotherapy in reducing the frequency of CD4+CD25+FoxP3+ Tregs and their suppressive function in the circulation of patients with hepatocellular carcinoma and in tumor tissues of breast cancer patients." (PMID 33532902, 2021). "Together, these results suggest that THOR-707 drives the proliferation of NK and CD8+ T cells in peripheral blood, tumor and spleen tissue without induction of suppressive CD4+ Treg subpopulations." (PMID 34373459, 2021). "Given their role in the negative control of anti-tumor immunity, future investigation will be needed to assess PD-L1 + expression on intrafollicular CD4 + T cells." (PMID 34267181, 2021). "Interestingly, we also found higher anti-tumor immune cells in the VEGF-high score subtype, including activated CD4+ T cell, activated CD8+ T cell and nature killer cell." (PMID 34284746, 2021).
tumor (continued). "At the early time point, when the in vivo OI signal peaked, CD4-Nb1 was widely distributed throughout the whole tumor, whereas no Cy5.5 signal was detected in the GFP-Nb-injected mice." (PMID 34956237, 2021). "Another recent phase I/Ib study tested the efficacy of a personalized neoantigen vaccine in newly diagnosed GBM patients and found the vaccination promoted neoantigen-specific CD4+ and CD8+ T cell responses and additionally increased the number of tumor-infiltrating T cells." (PMID 33496872, 2021). "In addition, we found that the percentages of Th1 cells (CD4+IFN-γ+) and IFN-γ+CD8+ cells were reduced in tumours from KO mice." (PMID 33654093, 2021). "These patients also had a significant decrease of lymphocytes and increased numbers of functionally suppressive CD4+CD25+ Tregs in the peripheral blood and tumor microenvironment, With a subsequent increase of CTLA4 expression on both T cells and breast cancer cells." (PMID 37305162, 2021). "In contrast, tumor CD4+ Th cells were most abundant in young non-stressed mice, but were significantly reduced (p<0.01) by stress." (PMID 34604038, 2021). "Studies have shown that the Wnt pathway may also regulate other immune compartments other than CD4+ and CD8+ T cells, such as in tumor latent competent cancers." (PMID 34072037, 2021). "The frequency of CD8+ and CD4+ T cells were not changed with propranolol treatment from tumor tissue and spleen in mice." (PMID 33981600, 2021). "Moreover, the depletion of Tregs in advanced primary tumors induces a strong CD4+ T cell and interferon (IFN)γ-dependent anti-tumor response." (PMID 33777750, 2021). "CD4 + and CD8 + T cells kill tumor cells via specific immune responses, especially CD8 + T cells." (PMID 33792840, 2021). "However, tumor-infiltrating CD8+ T and CD4+ T cells subjected to AXL inhibition showed a noticeable induction of PD-1 on their surface." (PMID 34778071, 2021). "Both tumor and colon had similar levels of CD103+CD39- CD4 or CD8 TRMs." (PMID 34680397, 2021). "For instance, some researchers claimed that CCR5 could promote breast cad gastric cancer progression, while others demonstrated that the expression of CCR5 in both CD4+ and CD8+ T cells was critical in boosting anti-tumor immune response." (PMID 34717291, 2021). "Furthermore, the detailed TCR repertoire analyses suggested that the observed increase in CD4+ and CD8+ T cells resulted from an expansion of T cells present in the tumor before targeted therapy." (PMID 33275172, 2021). "In contrast, control tumor lysates-treated DCs increased the frequency of Th2 (CD4+IL-4+), CD4, and CD8 regulatory T cell subtypes, none of which was observed with DCs loaded with PAM-lysates." (PMID 33915703, 2021). "CD4+ and CD8+ T cells are the most prominent effectors of anti‐tumor immune response." (PMID 34459003, 2021). "Careful analysis of CD3 T cells (with both CD4 and CD8 populations included) revealed that T cells isolated from tumours with TLS have different transcription signature from T cells isolated from tumours without TLS, and this also differs to T cells isolated from TLS themselves." (PMID 34054861, 2021). "The anti-tumor reactivity of expanded TIL from primary tumors previously treated with BCG immunotherapy were lower (33.3% vs. 82.6%, p=0.027) although T-cell phenotype (CD3+, CD4+, CD8+, and CD56+) was similar regardless prior of BCG therapy." (PMID 33717150, 2021). "Although CD4+ and CD8+ spleen cells from mice vaccinated with these LP-pulsed DCs produced IFN-γ in response to the immunizing peptide, their response to LLC1 tumor cells was barely detectable." (PMID 34771674, 2021). "Recently, Toda’s group evaluated the expression of PD-L1, IDO1, CD3, CD4, and CD8 in tumor tissues collected by biopsy or surgical resection from 56 OS patients, by comparing primary and metastatic lesions, and samples before neo-adjuvant chemotherapy (NAC) and after NAC." (PMID 34359840, 2021).
tumor (continued). "A study reported that in lung adenocarcinoma tumor growth was compromised in PCAF−/− mice, with reduced infiltration of CD4+Foxp3+ Treg cells but increased infiltration of host CD8 T cells, indicating that targeting PCAF reduces tumor volume and improves anti-tumor immunity." (PMID 34880761, 2021). "As expected, only after CD4+ T cell depletion did the tumor weight in host WT mice show no significant change between mice transferred with WT BMDMs and those transferred with Fats−/− BMDMs." (PMID 34262035, 2021). "Across all the SCLC tumor specimens assessed, CD8+ and CD4+ T cell per area cell count positively correlated with the T cell score computed from gene expression data, and both IHC-based T cell counts and gene expression-based T cell scores negatively correlated with NE scores." (PMID 33750914, 2021). "Furthermore, in the tumor-bearing mouse, MK615 treatment enhanced the CD4+/CD8+ ratios following irradiation and reduced tumor volume compared with the irradiated only group." (PMID 34122104, 2021). "In previous studies, the conclusions regarding the frequency and absolute value of CD4+ TSCM cells in different tumor sample types were not uniform." (PMID 34327142, 2021). "Moreover, an abundance of CD4 + and CD8 + T cells plays an important role in tumor response to immunotherapies." (PMID 34631703, 2021). "CD4+ and CD8+ T cells have anti-tumor activity in both primary and metastatic tumors." (PMID 34204474, 2021). "Furthermore, tumor-infiltrating Breg cells with increased expression of PD-L1 and TGF-β suppressed the proliferation of CD4+ T cells, CD8+ T cells, and NK cells." (PMID 34248142, 2021). "A significant decrease in CD4/CD8 and Treg/CD8 ratio in tumor tissue was demonstrated." (PMID 33987190, 2021). "CD4+ T cells mainly support CD8+ T toxic lymphocytes and enhance their anti-tumor immune effect." (PMID 34917126, 2021). "In this study, THBS2 expression did not correlate with tumor purity and showed significant positive correlation with infiltrating levels of B cell, CD4+ T cell, CD8+ T cell, macrophage, neutrophil, and dendritic cells in TIMER 2.0 database." (PMID 34471634, 2021). "In these organs DCs present tumor antigen-derived peptides in the context of Major Histocompatibility Complex (MHC) molecules of class I (MHC-I) and class II (MHC-II) to naïve CD8 and CD4 T cells, respectively." (PMID 34867987, 2021). "The genetic or pharmacological inhibition of Vps34 kinase activity using SB02024 or SAR405 (Vps34i) decreased tumour growth and improved mouse survival in multiple tumour models (melanoma and CRC) by inducing the infiltration of CD8+, CD4+ T effector cells and NK cells." (PMID 34367148, 2021). "Interestingly, in metastatic breast cancer, regulatory T cells can originate from the CD4+ T cells as a result of stimulation by the immunosuppressive cytokines such as IL-10 and TGF-β secreted by tumor-evoked B cells." (PMID 34885122, 2021). "Our study found that there was a positive correlation between the high-risk group and tumor-infiltrating immune cells, such as B cells, neutrophils, and macrophages, but a negative correlation with CD8+ T cells, CD4+ T cells, and monocytes." (PMID 34923955, 2021). "Initiation of TH1 type CD4+ T cell responses via DC-derived cytokines such as IL-12 is a crucial component in the anti-tumor response, reinforcing the expansion of CD8+ T cells and licensing CTLs for (tumor) killing." (PMID 34054859, 2021). "Infiltrating immune cells in the tumor microenvironment, mainly including tumor-infiltrating lymphocytes (B cells, CD8+ T cells, and CD4+ T cells) and other immune cells (macrophages, neutrophils, and dendritic cells), have become the focus of current tumor research." (PMID 34759950, 2021). "Combination therapy promoted a significant and sustained reduction of CD4+FoxP3+ Tregs in the EMT6 TME, without significantly affecting FoxP3− CD4+ tumor-infiltrating lymphocytes (TILs)." (PMID 34446712, 2021).
tumor (continued). "The expression level of SLC25A27 was positively correlated with tumor purity and the infiltration levels of CD4+ T cells, but not with the infiltration levels of CD8+ T cells, dendritic cells, B cells, macrophages, and neutrophil." (PMID 34868460, 2021). "The role of CD4 + effector T cells, if any, in mediating anti-PD-1 tumor control, is to date therefore not established." (PMID 33602280, 2021). "Moreover, we observed that EMP3 affected macrophages, causing inhibition of antitumour immunity via suppression of CD4+ and CD8+ T cell infiltration into GBM tumours and downregulation of CXCL9 and CXCL10 production by macrophages." (PMID 33964937, 2021). "Recently, it was also shown that TH9, but not TH2, differentiation of CD4+ CAR T cells promotes the function of CD8+ CAR T cells in the tumor environment." (PMID 34503109, 2021). "The relationship between the ratios of TILs FOXP3+ /CD8+, FOXP3+/CD4+ and CD4+/CD8+ and tumor recurrence was analyzed and only high FOXP3+/CD8+ and high FOXP3/CD4 + ratios were found to be associated with a decreased recurrence-free survival (p = 0.02 and p = 0.036, respectively)." (PMID 34952631, 2021). "Activation in the presence of CAFs induced phenotypic changes in both CD8+ and CD4+ T cells with upregulation of co-inhibitory receptors PD-1, Tim3 and LAG-3 as well as CD39 resulting in a phenotype resembling that of tumor infiltrating T cells." (PMID 34290905, 2021). "ALC, as a sensitive and accurate metric for measuring the number of CD4 cells, has never been studied to explore its value as a predictor of PsP versus true tumor progression in GBM patients." (PMID 33726710, 2021). "We next measured the abundance of CD4+ and CD8+ cells in the lungs, since altered immune cell numbers in the lung tissue may indicate differences in immune-mediated tumor cell clearance." (PMID 34556788, 2021). "Single-cell cytotoxicity assays of cytotoxic CD4+ T cells specific for tumor antigen (NY-ESO-1 and MAGE-A3), which were isolated using MHC class II tetramers, demonstrated their direct killing of tumor cells pre-treated with IFN-γ or stably transduced with CIITA to enhance MHC class II expression." (PMID 34910940, 2021). "Intraperitoneal administration of anti-CD4 or anti-CD8 depletion antibodies or IgG isotype control antibody was started a day before MBT-2 tumor inoculation, and oral administration of B. longum 420 was started 7 days after the tumor inoculation." (PMID 34589578, 2021). "This treatment effect was dependent on CD4 and CD8 T cells, as well as macrophages, highlighting the complex relationship between constituents of the TME, and the potential need for multi-targeted therapy to overcome tumour-mediated immunosuppression." (PMID 34733287, 2021). "It was also found that sEVs isolated from the serum of oral cancer mice expressing PD-L1 prevented the infiltration of CD4+ T and CD8+ T cells into the tumor microenvironment by binding PD-1, hence enhancing the proliferation and metastasis of these tumor cells." (PMID 34094979, 2021). "The overexpression of hypoxanthine phosphoribosyltransferase 1 (HPRT1) can contribute to the formation of an immunosuppressive tumor microenvironment by significantly reducing the activation of immune cells (B cells, CD8 + T cells, CD4 + T cells, macrophages, and neutrophils)." (PMID 34422810, 2021). "The main mechanism of tumor immune surveillance in the TME is CD8+ cytotoxic T cells response, while Tregs with CD4+ CD25+ infiltration could inhibit T cells activity and ulteriorly promote tumor progression." (PMID 34858852, 2021). "However, in the context of CD4+T or NK cells deletion, the LLC or B16F10 tumor-bearing mice processed by IL-10 or Ad-hTERT presented shrinking tumor and improved survival compared with PBS control group." (PMID 33717103, 2021).